MKI67 (marker of proliferation Ki-67)
Diseases named in the same sentence as MKI67 in open-access papers (continued):
Sharing a sentence is not in itself a finding about the gene and the disease.
cancer (2,879 papers, 1988 to 2026). A tumor composed of atypical neoplastic, often pleomorphic cells that invade other tissues. "Although low levels of Ki‐67 are associated with cancer senescence, DR‐LSCC exhibited proliferative activity via Ki‐67 immunofluorescent inspection contradicting the MKI67 gene results." (PMID 40385549, 2025). "Many TACT markers used in the present study, such as EPCAM and MKI67, have been implicated in fundamental biological processes relevant to various cancer types, including cell proliferation and EMT." (PMID 40003943, 2025). "In alignment with these findings, our study revealed a consistent positive correlation between CaGalT1 expression levels and MKI67, the gene encoding the Ki‐67 protein, across almost all examined cancer types." (PMID 40548474, 2025). "Other notable genes include the MKI67, a well-established marker of cell proliferation that has been linked to several cancers, including MM and its precursor stage, MGUS." (PMID 40941618, 2025). "The increased expression of MKi67 is often observed in proliferating cells and is associated with a higher growth rate of cancer cells and poorer prognosis." (PMID 38674285, 2024). "MKI67, also known as Ki-67, is another proliferation-associated marker commonly used in cancer research." (PMID 38250721, 2024). "As expected, markers of liver differentiation, such as EPHX2, showed downregulation, while those associated with cancer proliferation, such as MKI67, increased." (PMID 39199347, 2024). "The gene encoding the Ki-67 protein (MKI67) acts as an intracellular signaling promoter of division and is overexpressed in conditions such as cancer." (PMID 38931326, 2024). "We also showed that higher MKI67 expression value is associated with higher grade cancer and found statistically significant differences with lower grade cancer in both test and external data." (PMID 37174035, 2023). "High proliferation is often a sign of aggressive behaviors in cancer, and high expression of MKI67 has been linked to worse DFS in cancer patients." (PMID 35562738, 2022). "Coexpression analysis revealed that KIF11, KIF18B, KIF23, and MKI67 were positively associated with the expression of IQGAP3 in all cancer types presented in the heatmap." (PMID 36164370, 2022). "The present work focuses on exploring the prognosis prediction performance of MKI67 and its associations with T cell activity and immune infiltration within numerous cancers, especially hepatocellular liver carcinoma (LIHC)." (PMID 34724892, 2021). "According to TCGA-based analysis, MKI67 upregulation is associated with many cancers’ dismal prognostic outcomes (PAAD, SARC, KIRP, and UVM)." (PMID 34724892, 2021). "We conducted comprehensive analysis on the associations of MKI67 level with patient survival from 3 large-scale cancer databases consisting of sufficient samples to assess the prognosis prediction performance of MKI67 for cancer." (PMID 34724892, 2021). "MKI67, the gene which encodes the proliferation-associated protein Ki67 has significantly higher expression in genome doubled cancers." (PMID 32823571, 2020). "Moreover, we compared the potential association of MKI67 expression with eight immune checkpoint pathway genes in pan-cancer." (PMID 40070823, 2025). "Examination of key cancer-associated markers revealed distinct subtype-specific expression patterns, with the proliferation marker MKI67 showing higher expression in malignant subtypes 2 and 6, while the potential stem cell marker CD44 was elevated in subtype 3." (PMID 40650680, 2025). "Briefly, myeloid cells (LYZ+), lymphocytes (CD3D+), osteoclasts (ACP5+), endothelial cells (CLDN5+), perivascular-like cells (PVL) (RGS5+TAGLNhigh), cancer-associated fibroblasts (CAFs) (TAGLNlowACTA2+) and proliferative cells (MKI67+) were identified in the study." (PMID 36596773, 2023). "MKI67 has been proposed as a potential marker for several cancers and may be linked to the diagnosis of PH." (PMID 36389368, 2022).
cancer (continued). "Therefore, we further analysed the association of MKI67 levels with immune cell infiltration degrees within 39 cancers based on the TIMER database." (PMID 34724892, 2021). "Nonetheless, the association of MKI67 levels with T cell activity, prognosis, and immune infiltration in diverse cancers remains unclear." (PMID 34724892, 2021). "PRS was positively correlated with the MKI67 score, which proves that the high-risk group may be closely related to the regulation of cancer cell cycle and cancer cell proliferation (Cor = 0.295, P = 4.865e-11)." (PMID 33619234, 2021). "Their potential functions in NSCLC were explored through their NSCLC-specific co-expression network analysis, their correlations with immune infiltrations, immunomodulator gene expressions, MKI67 expression and their associations with anti-cancer drug sensitivity." (PMID 32265992, 2020). "This study's aim was to clarify the regulatory roles of the MKI67 rs11016073 and APOB rs1367117 polymorphisms in the relationship between blood Pb levels and cancer risk." (PMID 41828541, 2026). "Patients we collected and TCGA database displayed an intimate relationship between MKI67 expression level and prognosis across varied cancer types." (PMID 40070823, 2025). "A study of human and mouse cancers defined cancer cells (among epithelial cells) as patient-specific clusters with an enrichment of Mki67 expression." (PMID 40846797, 2025). "Among the proliferation‐associated genes analyzed—including MKI67, PCNA, MCM2–7, MAP17 (PDZK1IP1), and PLK1—many demonstrated strong positive correlations with C1GALT1 expression in cancers such as pancreas, bladder, breast, stomach, prostate, and liver." (PMID 40548474, 2025). "Notable downregulated genes included Mki67, Ccn1, Muc1, Atf3, Ntrk2, Arid5b, Igf1r, Igf2bp2, Cd47, and Cd37 (oncogenic function) and integrin-related genes, Itga7, Itga11, Itgam and Notch1 (cancer stem cell markers)." (PMID 39946195, 2025). "The integrative analysis identified PROX1+ LEC subsets, JAM2+ BECs, COL1A1+ stromal cells, PTPRC+ leukocytes, including MZB1+ plasmablasts, KRT19+ cancer cells, and MKI67+-proliferating cells." (PMID 41249124, 2025). "Immunohistochemical diagnosis of MM is mostly based on melanocyte-specific markers such as PMEL, MLANA, or TYR, along with relatively unspecific and pleiotropic cancer biomarkers like S100B, and proliferation-related markers like MKI67." (PMID 40004203, 2025). "The nuclear protein Ki-67, encoded by the MKI67 gene, is a widely recognized marker of cellular proliferation and serves as a marker for assessing cell division in cancer research and clinical settings." (PMID 40666093, 2025). "Especially, Th1 and Th2 CD4+ T cells were most positively correlated with MKI67 expression in various cancer types." (PMID 40070823, 2025). "To investigate the prognosis value of MKI67 expression among various cancer types, we then explored the correlation between MKI67 expression and prognosis of patients within different cancer types based on the TCGA database." (PMID 40070823, 2025). "For the overall group analysis, patients in Groups 1 and 2 displayed similar expression patterns, particularly the downregulation of cancer-associated genes (Fas, NOS2, VEGF-A, NR4A3, MKi67, and EpCAM), as well as the pro-inflammatory cytokine IL-6." (PMID 40359186, 2025). "We identified the MKI67 mRNA expression characteristics between pan-cancer and adjacent normal tissues using the TIMER2 database and TCGA data." (PMID 40070823, 2025). "In line with the correlation analysis, blood vessel enriched zone of BM had substantial MKI67 positive cancer cells, but reduced in blood vessel-free zone." (PMID 40883281, 2025). "Cancer cells are defined as cells expressing high MKI67, CAV1, and CTNNB1 and present spatial variations in the expression of VEGFC, FN1, and NRP1." (PMID 40081369, 2025).
cancer (continued). "In particular, MKI67 expression were most positively correlated with Th1 and Th2 CD4+ T cells across various cancer types, while MKI67 expression were largely negatively correlated with Macrophage M2 cells across various cancer types." (PMID 40070823, 2025). "In this phase IIA clinical study, upregulated expression of cancer-associated genes, including those linked to tumorigenesis and metastasis, such as VEGF-A, NR4A3, MKi67, and EpCAM were detected as early as Day 1 in the iCCA patients (Groups 1, 2, and 3)." (PMID 40359186, 2025). "The cancer model utilizing the MKI67+ TCs subpopulation (MTRS) successfully classified patient survival and linked with immune infiltration patterns and medication responses." (PMID 40842994, 2025). "Previous studies have shown that MKI67 affects immune infiltration and T-cell fatigue and serves as a prognostic biomarker in cancers, especially HCC." (PMID 40421085, 2025). "Above all, the prognosis value of MKI67 expression in several cancer types was precisely identified in our validation cohort and TCGA database, of which the results were generally consistent and reliable." (PMID 40070823, 2025). "We further focused on the relationship between MKI67 expression and OS using Kaplan-Meier analysis based on the 10028 cancer patients collected and TCGA database." (PMID 40070823, 2025). "Above all, MKI67 expression plays distinct and essential roles in the prognosis of various cancer types." (PMID 40070823, 2025). "MKI67 plays a role in controlling the separation of chromosomes during cell division and is a reliable marker for identifying the growth of cancer cells." (PMID 38464517, 2024). "Our analysis of ER+ PDXs, including ST and scRNA‐seq analyses, indicated that the MKI67+ ST_2 compartment was the major driver for the proliferation of ER+ cancers." (PMID 38282415, 2024). "MKI67, also known as proliferation marker Ki-67, is the subject of hundreds of papers chronicling its involvement in numerous kinds of cancer." (PMID 39009698, 2024). "Conversely, MKI67, as a proliferation marker, showed significantly upregulated mRNA and protein expression across various cancers." (PMID 38928396, 2024). "Antigen Ki-67, also known as Ki-67 or marker of proliferation Ki-67 (MKI67), is a protein whose expression reliably correlates with cancer proliferation." (PMID 39126074, 2024). "We further investigated the expression and distribution of proliferation-related (CDK4, MKI67) and cancer-related epithelial (KRT15, CD24) cell marker genes among each cluster." (PMID 36811599, 2023). "We obtained 12 major cell clusters, consisting of T cells, B cells, Natural Killer (NK) cells, plasma cells, macrophages, MKI67+ progenitor cells, endothelial cells, mesenchymal cells, fibroblasts, neutrophils, and epithelial/cancer cells." (PMID 37686305, 2023). "Proliferative cancer cells highly expressed proliferation-related genes (MKI67, TOP2A, and TPX2); they also had the highest CytoTRACE score, reflecting strong proliferative potential and higher stemness characteristics." (PMID 37853464, 2023). "The doxorubicin treatment displayed a favorable gene signature among surviving cancer cells with low proliferation (MKI67) and pluripotency features (NANOG, POU5F1), in comparison to 5-fluorouracil showing low proliferation but increased pluripotency." (PMID 38124067, 2023).
cancer (continued). "As demonstrated in the top DEGs, specifically cancer stem lineage clusters expressed high levels of stemness feature genes (MKI67, CD44, CD24, and PROM1) and key DEeRNAs (PHLDA1 and RASD1)." (PMID 36092920, 2022). "At the same time, RNASEH2A and HENMT1 were positively correlated with the expression of clinical markers (MKI67) in cancer tissues." (PMID 35449547, 2022). "In both IP and IS injection models, we didn't observe a proliferation disadvantage following collagen VI KO in these cancer cells, as measured by Ki-67 (also known as MKI67) positivity in metastatic foci." (PMID 36546396, 2022). "Intriguingly, we found that the expression of YAP1 was positively correlated with the expression of MKI67 in most of the cancer types." (PMID 35685435, 2022). "For instance, the expression of the Ki67 gene (MKI67), the putative proliferation marker, was found to be tightly associated with levels of FAM72A, B, and D across different cancers." (PMID 36613817, 2022). "The association of NR2F1 levels with the Nottingham histological grades and the cell proliferation marker MKI67 was studied for the pathological assessment of cancer cell proliferation." (PMID 35740627, 2022). "The high-FRGPI group was marked with significantly higher MKI67 expression and exhibited higher cancer proliferation potential." (PMID 35368652, 2022). "There is little information regarding MKI67 gene expression compared to what it known about the significance of KI67 protein expression for cancer diagnosis." (PMID 36389368, 2022). "Further in-depth analysis characterized CCNA2/MKI67/KIF11:miR-30a-5p:VPS9D1-AS1 axis-related cell cycle as a prognostic biomarker, and all of these RNAs were cancer-associated crucial genes." (PMID 35186743, 2022). "As expected, normalized MKI67 read counts were higher in all nine cancers when compared to the respective adjacent normal tissues." (PMID 36581993, 2022). "Specifically, MKI67 (a known nuclear marker of proliferation) was highly expressed in all cell clusters, indicating high cellular proliferative activities in these cancer cells." (PMID 36092920, 2022). "Some BIIGs were upregulated in multiple cancer types: Top2a, Mki67, Rrm2, Mcm6, and Spp1 were upregulated in more than eight cancer types, while Emp1, Ptx3, and Socs3 were upregulated in seven cancer types." (PMID 36605216, 2022). "According to our results, MKI67 expression is related to the survival of diverse cancers, such as LIHC." (PMID 34724892, 2021). "Enhanced UPR was associated with the clinical parameters of HCC progression, such as cancer stage and multiple parameters of cell proliferation, including histological grade, mKI67 gene expression, and enrichment of cell proliferation-related gene sets." (PMID 34503253, 2021). "Mki67+ cells, which divide actively, were separated in a single cluster in both datasets (clusters 9 and 8 for the control and cancer organoids, respectively)." (PMID 34785704, 2021). "To better evaluate MKI67 levels in human cancers, we analysed MKI67 levels in various TCGA-derived cancers based on RNA-seq data." (PMID 34724892, 2021). "The present study analysed MKI67 expression with prognosis expression profiles in different types of cancers based on individual datasets from Oncomine and 33 TCGA-derived cancers in GEPIA2." (PMID 34724892, 2021). "An example of a PrCa-upregulated gene with a very low (close to zero) GD value is MKI67 (a marker of proliferation Ki-67), which codes for a nuclear protein that has become a well-studied immunohistochemical marker of cancer proliferation." (PMID 34680307, 2021). "In contrast to the importance of Ki-67 protein expression for cancer diagnostics, only limited information is available on how the MKI67 gene is expressed." (PMID 34183782, 2021). "The positive MKI67 rate (referred to as the labelling index) is suggested to be related to the clinicopathological characteristics or the survival of cancers, such as LIHC." (PMID 34724892, 2021).
cancer (continued). "The expression of Mki67 increased over pseudotime in the control organoids but peaked in the middle of the trajectory in the cancer organoids." (PMID 34785704, 2021). "Cancer cells show high MK167 protein expression, and the positive MKI67 rate (referred to as the labelling index) is related to the clinicopathological characteristics and survival of diverse cancers, such as LIHC." (PMID 34724892, 2021). "The common histological assessments of grade and MKI67 expression are used as clinical correlates to recognize degrees of cell proliferation in cancer." (PMID 34503253, 2021). "We observed that samples with high chromatin accessibility of CERES have high expression of CDKN1C, accompanied by low expression of genes involved in cancer cell proliferation (MKI67 and PCNA) and aggressiveness (FOXM1)." (PMID 34272384, 2021). "Different MKI67 levels measured in diverse cancers from distinct databases can provide a novel data extraction method and help illustrate the mechanisms associated with diverse biological characteristics." (PMID 34724892, 2021). "The results in this work indicate the potential of MKI67 as a prognostic biomarker for several cancers, particularly LIHC." (PMID 34724892, 2021). "We found that DEPTH scores positively correlated with MKI67 expression levels in 13 individual cancer types (FDRSp < 0.05)." (PMID 32917965, 2020). "In a range of common cancer types, HIF-1α was positively associated with the proliferation marker Ki67 (Mki67), and several studies report that HIF overexpression in cells can promote cell proliferation." (PMID 32571767, 2020). "MKI67 gene codes ki-67, which is one of the most commonly used molecular markers of cancer cell proliferation." (PMID 32357442, 2020). "After normalization to the canonical cancer cell proliferation marker MKI67, all four DNMTs showed significantly reduced expression in EOC as compared to NO, and in GDHO (+) vs. GDHO (–) EOC." (PMID 32213861, 2020). "More specifically, ex vivo culturing encouraged the expansion of Epcam+/Mki67+ cancer cells from 7.4% to 30.1% of the total cells." (PMID 32183351, 2020). "We examined the association between the amount of intratumoral adipocyte and MKI67 expression, the most commonly used marker of cancer cell proliferation in the clinical setting." (PMID 32796516, 2020). "The overexpression on MKI-67 in cancers can indicate a disruption in the proliferation pathway resulting to the appearance of carcinomas." (PMID 32153656, 2020). "In particular, genes like MYC, MKI67, CTNNB1, PCNA, NKX3.1, ACPP and kallikreins are warranted further investigation as diagnostic markers for cancer and cell proliferation." (PMID 31519932, 2019). "A second set consisted of an additional 15 cancer-related genes (Nf1, Mki67, Mllt4, Fgfr2, Ctnnb1, Fat1, Clp1, Fat4, Arid1a, Nat1, Nat2, Setd2, Impg1, Nbas and Npat)." (PMID 29925311, 2018). "MKI67 is a protein that is widely used as a marker for cell proliferation, and its increased expression in human cancer specimens generally denotes an aggressive phenotype." (PMID 30538721, 2018). "Ki67, also known as Ki67 antigen or MKI67 (marker of proliferation Ki67), has been a well-established marker for predicting the clinical outcomes for patients with several types of cancer." (PMID 30341240, 2018). "A significantly positive correlation between MKI67IP (NIFK) and MKI67 (Ki-67) was observed in almost all cancer types." (PMID 26984280, 2016). "Similar to the results of CSC marker genes, semiquantitative RT-PCR analysis showed that ADSCs strongly upregulate the growth-related genes in cancer cells, including MKI67 (4T1, 7.44 ± 2.43; CT26, 2.93 ± 0.29) and PCNA (4T1, 3.85 ± 1.02; CT26, 7.09 ± 1.54)." (PMID 25797257, 2015). "Among them, 10 were shown to be involved in either homology-directed DNA repair or centrosome duplication control including the well- known cancer marker MKI67." (PMID 22956898, 2012).